MYO9B (myosin IXB)
Diseases named in the same sentence as MYO9B in open-access papers:
MYO9B is named in the same sentence as 36 diseases in open-access papers, as found by Europe PMC text mining. Sharing a sentence is not in itself a finding about the gene and the disease. The quoted sentences say what the papers report.
celiac disease (6 papers, 2009 to 2025). An autoimmune genetic disorder with an unknown pattern of inheritance that primarily affects the digestive tract. "MYO9B is a candidate gene that is reportedly associated with celiac disease and diabetes type 1 (DM type 1)." (PMID 27556856, 2016). "Pathologies that are apparently unrelated have increasingly been shown to share common genetic risk factors, such as celiac disease and schizophrenia in terms of MYO9B." (PMID 19175939, 2009). "MYO9B lies on chromosome 19p13.1, which has been linked to both celiac disease and IBD." (PMID 27556856, 2016). "A previous Dutch study first suggested MYO9B as a susceptibility gene for celiac disease." (PMID 27556856, 2016). "As MYO9B is related to inflammatory bowel diseases and celiac disease, the use of Myo9b KO mice has been mostly limited in studies of immune cells." (PMID 32244264, 2020).
inflammatory bowel disease (5 papers, 2016 to 2023). A spectrum of small and large bowel inflammatory diseases of unknown etiology. "Myosin IXB (MYO9B) gene polymorphisms have been extensively investigated in terms of their associations with inflammatory bowel disease (IBD), with contradictory results." (PMID 27556856, 2016).
lung carcinoma (5 papers, 2020 to 2024). "The myosin IXB (MYO9B) gene encodes an F-actin–based cytoskeletal motor protein, which has been reported to suppresses the RhoA activity in lung cancer cells." (PMID 36127319, 2022). "Recent investigations have shown the role of Myo9b-RhoA in mediating the inhibitory effect of SLIT2 on lung cancer cell migration." (PMID 33318575, 2020). "Myo9b is overexpressed in lung cancer tissue, and it interacts with ROBO1-ICD through its RhoGAP domain, which suppresses the Myo9b RhoGAP activity." (PMID 33318575, 2020). "High levels of MYO9B have been shown to promote actin reorganization by reducing filaments and to stimulate metastasis by breaking down stress fibers and reducing cell adhesion, thereby enhancing the cancer phenotype in both prostate and lung cancer." (PMID 38745208, 2024). "Interestingly, MYO9B was shown to physically interact with the intracellular domain of Robo1 in lung cancer cells, leading to MYO9B inhibition and RhoA activation upon Slit addition." (PMID 37675403, 2023).
breast carcinoma (3 papers, 2017 to 2024). "Furthermore, MYO9B knockdown in breast cancer cells suppressed their in vitro proliferation, migration, and invasiveness." (PMID 38335839, 2024). "Finally, only 1 (BCAS4/BCAS3), 1 (BSG/NFIX), 2 (STX16/RAE1, RAB22A/MYO9B) and 0 fusions have been reported by all the tools within the considered breast cancer cell lines." (PMID 28114882, 2017).
diabetes (3 papers, 2013 to 2023). "Consequently, ALR Myo9b KI and Myo9b deficiency in DCs delay diabetes onset and prevent the progression of autoimmune diabetes in NOD mice." (PMID 37749140, 2023). "In addition to CD and IBD, MYO9B has also been associated with susceptibility to type 1 diabetes mellitus in a Spanish cohort." (PMID 24386489, 2013). "In spite of the recent studies that have shown relationship between diabetes and the expression of molecular motors, as myosin-IIB, myosin heavy-chain, myosin-Va, and myosin-IXB, the pathways linked among myosin expression, oxidative stress, and diabetes mellitus are still unclear." (PMID 24982856, 2013). "Given the crucial role of β cell death in diabetes progression, we then assessed the impact of Myo9b KI on β cell viability." (PMID 37749140, 2023). "The association of variants of MYO9B with acute pancreatitis points to a possible shared genetic mechanism that impairs mucosal barrier function not only in acute pancreatitis, but also in CD, IBD and type 1 diabetes mellitus." (PMID 24386489, 2013). "Here the author show, by comparing the diabetes-sensitive NOD mouse strain with its congenic, diabetes-resistant ALR strain, and by genomic analyses of T1D patients and control, that mutations in the Myo9b gene may alter dendritic cells to contribute to autoimmune diabetes onset." (PMID 37749140, 2023).
autoimmune disease (2 papers, 2019 to 2023). A disorder resulting from loss of function or tissue destruction of an organ or multiple organs, arising from humoral or cellular immune responses of the individual to their own tissue constituents. "MYO9B is a RhoA-specific GAP protein that has been associated with autoimmune disease—celiac disease." (PMID 30934641, 2019). "In their search for a candidate gene that could fit the long-thought association between autoimmune diseases and schizophrenia, Jungerius and colleagues have tested the hypothesis that MYO9B is the candidate gene." (PMID 30934641, 2019).
pancreatitis (2 papers, 2020 to 2022). Inflammation of the pancreas. "Certain genes, such as the myosin IXB (MYO9B) gene and its two close-connected adaptor genes, MAGI2 and PARD3, have been associated with pancreatitis as well as IBD." (PMID 32831829, 2020). "Other genetic factors related to pancreatitis are Calcium Sensing Receptor (CASR), Claudin 2 (CLDN2), Carboxyl Ester Lipase (CEL), Cathepsin B (CTSB), Myosin IXB (MYO9B), Ubiquitin Protein Ligase E3 Component N-Recognin 1 (UBR1), and Fucosyltransferase 2 (FUT2)." (PMID 36434531, 2022).
prostate carcinoma (2 papers, 2019 to 2024). A carcinoma that arises from epithelial cells of the prostate gland. "Similarly, Myosin IXB (MYO9B) is implicated in the progression of lung and prostate cancer, enhancing cancer cell migration and reducing survival." (PMID 38335839, 2024). "One study demonstrated that MYO9B was involved in the migration of prostate cancer cell lines and might be important for metastasis (Makowska, Hughes, White, Wells, & Peckham, 2015)." (PMID 30809968, 2019).
schizophrenia (2 papers, 2009 to 2019). A major psychotic disorder characterized by abnormalities in the perception or expression of reality. "Interestingly, they show strong correlation between MYO9B associated SNPs and schizophrenia." (PMID 30934641, 2019).
Abdominal obesity (1 paper, 2019). Excessive fat around the stomach and abdomen. "The top four CpGs that were found to be differentially methylated between individuals with and without abdominal obesity were located at the genes c13orf36, ZC3H12D, MYO9B, and KCNG3 in females; and JPH3, TCP11L1, and GRIK3 in males (one CpG had no annotated gene)." (PMID 31212707, 2019).
acute pancreatitis (1 paper, 2013). An acute inflammatory process that leads to necrosis of the pancreatic parenchyma. "By analyzing a combined cohort of Dutch and German patients with acute pancreatitis, we found an association of two genetic variants in MYO9B for susceptibility to this disease." (PMID 24386489, 2013). "The prevalence of MYO9B haplotypes in the combined Dutch and German cohorts of patients with acute pancreatitis and controls reconstructed from genotyped SNPs and their association with acute pancreatitis." (PMID 24386489, 2013). "In this analysis, four of the MYO9B SNPs were found to be associated with acute pancreatitis." (PMID 24386489, 2013). "We investigated genetic variation in MYO9B, PARD3 and MAGI2 for association with acute pancreatitis." (PMID 24386489, 2013). "We performed a candidate gene study for MYO9B, PARD3 and MAGI2 looking for susceptibility to acute pancreatitis." (PMID 24386489, 2013). "Five single nucleotide polymorphisms (SNPs) in MYO9B, two SNPs in PARD3, and three SNPs in MAGI2 were studied in a Dutch cohort of 387 patients with acute pancreatitis and over 800 controls, and in a German cohort of 235 patients and 250 controls." (PMID 24386489, 2013). "We have shown that MYO9B may be involved in acute pancreatitis, possibly due to its potential role in regulating the intestinal barrier function." (PMID 24386489, 2013). "We therefore adopted a candidate gene approach to test genetic variants in MYO9B, PAR3D and MAG12 for their potential association with acute pancreatitis in two independent cohorts: a Dutch cohort of 387 patients and more than 800 controls, and a German cohort of 235 patients and 250 controls." (PMID 24386489, 2013).
anemia (1 paper, 2022). A reduction in the number of red blood cells, the amount of hemoglobin, and/or the volume of packed red blood cells. "Although mutations in G6PD and HBA2 are associated with anemia and human disease, SEC14L4 and MYO9B are not previously known to affect RBC function." (PMID 34793330, 2022).
autism (1 paper, 2020). Persistent deficits in social interaction and communication and interaction as well as a markedly restricted repertoire of activity and interest as well as repetitive patterns of behavior. "Using WES and TADA analysis of rare coding variations of autism patients, MYO9B was identified as a gene strongly enriched for variants likely to affect autism risk." (PMID 32244264, 2020).
Autoimmunity (1 paper, 2023). The occurrence of an immune reaction against the organism's own cells or tissues. "Since NOD mice also spontaneously develop autoimmune co-morbidities other than autoimmune diabetes, we therefore examined the impact of Myo9b on the development of systemic inflammation and autoimmunity in 10- to 12-week-old prediabetic mice." (PMID 37749140, 2023).
brain tumors (1 paper, 2024). "Some of the frequently mutated genes have been rarely reported in brain tumors according to the COSMIC database: EPH2B (67% vs 1.11%), DICER1 (67 vs 1.25%), KMT2B (67% vs 1.46%), ATRX (67% vs 13.95%) as well as several muscular genes (DMD, MYO10, MYO9B, MYH6) (P < .00001, Fischer exact test)." (PMID 39233831, 2024).
colon adenocarcinoma (1 paper, 2021). "Moreover, only one meta-analysis showed that coffee polyphenols, caffeic acid and chlorogenic acid increased the MYO9B, PTPN11 and CDH1 gene expressions in un-stimulated colon adenocarcinoma HT29 cells." (PMID 33806347, 2021).
coronary artery diseases (1 paper, 2025). "MYO9B, a risk factor for coronary artery diseases, can enhance vascular diseases through modulating vascular cell motility." (PMID 40727388, 2025).
G6PD deficiency (1 paper, 2022). An X-linked genetic condition caused by alterations in the gene G6PD that result in moderately to severely decreased activity levels of the enzyme glucose-6-phosphate dehydrogenase. "Donor G6PD deficiency and polymorphisms in SEC14L4, HBA2, and MYO9B genes were associated with decreased hemoglobin increments." (PMID 34793330, 2022).
liver cancer (1 paper, 2022). An epithelial or non-epithelial malignant neoplasm that arises from the liver. "Of these DEGs, SERINC1 and MYO9B were previously reported as potential driver genes in liver cancer." (PMID 36712866, 2022).
metastatic tumors (1 paper, 2020). "In PCa, Myo1b, Myo6, Myo9b, Myo10, and Myo18a were expressed at higher levels in high metastatic potential cells, and especially Myo1b and Myo10 were expressed at higher levels in metastatic tumors." (PMID 33292248, 2020).
myocardial infarction (1 paper, 2024). Gross necrosis of the myocardium, as a result of interruption of the blood supply to the area, as in coronary thrombosis. "The involvement of genes such as AGPS, MYO9B, PYGB, TOM1, UBA52, and UBB in myocardial infarction is first reported in this study." (PMID 39872885, 2024).
neuropathies (1 paper, 2025). "We also compared the clinical presentations of Iranian and Italian patients expanding the clinical and mutational spectrum of MYO9B-related neuropathies." (PMID 40382695, 2025).
optic atrophy (1 paper, 2025). A disorder characterized by loss of optic nerve fibers. "For example, mutations in PLEKHG5, encoding a GEF that regulates autophagy of synaptic vesicles in axonal terminals, cause recessive intermediate CMT, while variants in MYO9B, encoding a RhoGAP, have recently been shown to cause CMT type 2 (CMT2) and optic atrophy." (PMID 41086021, 2025). "Interestingly, the corresponding MYO9B gene has recently been associated with a CMT2 subtype and isolated optic atrophy." (PMID 41086021, 2025).
osteosarcoma (1 paper, 2020). A usually aggressive malignant bone-forming mesenchymal neoplasm, predominantly affecting adolescents and young adults. "A recent study implicates MYO9B in the regulation of constitutive activity of RhoA to generate self-limiting cellular contraction patterns in the human osteosarcoma cell line, U2OS83." (PMID 32807784, 2020).
peritonitis (1 paper, 2014). Inflammation of the peritoneum (tissue that lines the abdominal wall and covers most of the organs in the abdomen). "This impaired migration was reflected in vivo, where Myo9b knockout mice showed a severe reduction of monocytes and macrophages recruited to the peritoneal cavity using an experimental model of C5a-induced peritonitis." (PMID 24466350, 2014).
virus infections (1 paper, 2025). "In this study, we have explored the role of Myo9b in virus infection using VSV-G-pseudotyped HIV as a model to infect a myeloid cell line (U937)." (PMID 40167026, 2025). "To enquire upon Myo9b participation in virus infections, we have silenced Myo9b in U937 and Jurkat cells and infected them with vesicular stomatitis virus glycoprotein (VSV-G)-pseudotyped HIV-1." (PMID 40167026, 2025). "In this work, we used the monocytic cell line U937 infected by HIV-1 pseudotyped with vesicular stomatitis virus glycoprotein (VSV-G) as a model to enquire upon the role of Myo9b in viral infection." (PMID 40167026, 2025). "This study suggests that the control exerted by Myo9b over the RhoGTPase system can be important in protecting immune cells from virus infections." (PMID 40167026, 2025). "This could explain the less pronounced effect of Myo9b silencing in virus infection of Jurkat cells." (PMID 40167026, 2025). "We observed that Myo9b knockdown led to an important increase in virus infection and release." (PMID 40167026, 2025). "Finally, we have also observed an increment in virus internalization and fusion in cells knockdown for Myo9b, which may explain the increase in virus infection." (PMID 40167026, 2025).
cancer (7 papers, 2018 to 2025). A tumor composed of atypical neoplastic, often pleomorphic cells that invade other tissues. "Among the 10 phosphopeptides upregulated in the high relapse-risk group, KIAA1522, DCK, FOXO3 and MYO9B are notable for their association with aggressive cancer phenotypes." (PMID 38745208, 2024). "Using genome-wide pleiotropy and colocalization analysis, we identified 60 colocalized susceptibility loci shared by CAD and site-specific cancer, of which 43 are novel, including loci at TERT, MYO9B, and SREBF1." (PMID 40874306, 2025). "The human myosin IXb (MYO9B) protein is mostly studied in cancer cell lines, where it localizes to sites of actin polymerization." (PMID 30123108, 2018). "These included multitrait colocalization at 6 loci with a consistent direction of effect between CAD and cancer (ABO, PGAP3, ANGPTL4, SREBF1, HAUS6, and SYNJ2BP) and 7 with an opposing direction (CDKN1A, RGS19, CALCRL, SF3A3, LAMC1, MYO9B, and MIA3)." (PMID 40874306, 2025).
infection (2 papers, 2020 to 2025). The state of being infected such as from the introduction of a foreign agent such as serum, vaccine, antigenic substance or organism. "Myo9b-silenced lymphocytic Jurkat cells were also more susceptible to infection by both HIV carrying WT Env and VSV-G-pseudotyped virus, although not to the same extent as U937 cells." (PMID 40167026, 2025). "Myo9b-silenced U937 showed a remarkable increase of above ten times more HIV-VSV-G infection than control cells." (PMID 40167026, 2025). "Analysis of the spatial proteome unravelled the coexpression of Myo9b and F4/80 in the infected urothelium, indicating that macrophages have entered the urothelium upon infection." (PMID 32112048, 2020). "Taken together, our data suggests that Myo9b might hinder viral entry and infection by controlling the activity of RhoGTPases in immune cells." (PMID 40167026, 2025). "We took the opportunity to test whether Myo9b silencing would affect infection with an HIV virus expressing only the HIV glycoprotein (gp120/gp41)." (PMID 40167026, 2025). "Finally, we observed that Myo9b silencing led to a rise in virus internalization and fusion, which could account for the higher levels of cell infection." (PMID 40167026, 2025). "We conclude that, in the absence of Myo9b, more active RhoGTPases led to increased virus internalization and subsequent infection." (PMID 40167026, 2025). "To test whether inhibition of RhoGTPases could affect HIV infection in U937 control or Myo9b-silenced cells, we treated these U937 with inhibitors to RhoA, B and C (C3) or to Rac1 (NSC23766) for 4 h before infection with VSV-G-pseudotyped HIV-1." (PMID 40167026, 2025). "To test whether the absence of Myo9b also affected the infection of a different cell type, we silenced Myo9b in Jurkat cells using lentivirus-carried shRNA (about 47% silencing)." (PMID 40167026, 2025).
intestinal disease (2 papers, 2022 to 2023). "Differential alternative splicing (AS) genes, such as Myo9b, Lsp1, and Git2, have major functions in intestinal diseases." (PMID 35496266, 2022). "Since substantial evidence exists for comorbidity between intestinal disease-related gut permeability and T1D35,36, two human studies have been performed to evaluate the effects of MYO9B gene polymorphisms on T1D patients, focusing on the most studied SNPs Rs962917, Rs2279003, and Rs230576423,24." (PMID 37749140, 2023).
gastrointestinal disorders (1 paper, 2019). "Polymorphisms in TJ-related genes MAGI2, PARD3, and MYO9B that potentially influence the homeostasis of the intestinal barrier have been associated with risk of gastrointestinal disorders like CD and IBD." (PMID 31921880, 2019).
MYO9B also shares sentences with these, for which no sentence is quoted: tumour (4 papers); diabetes type 1 (2); melanoma (2); rheumatoid arthritis (1); sensory peripheral neuropathies (1); systemic lupus erythematosus (1).